RNASE1 (ribonuclease A family member 1, pancreatic)
Diseases named in the same sentence as RNASE1 in open-access papers (continued):
Sharing a sentence is not in itself a finding about the gene and the disease.
cancer (continued). "Our study elucidates the role of RNase1 in mediating tumor resistance to immunotherapy and reveals an RNase1-mediated immunosuppressive tumor microenvironment, highlighting the potential of targeting RNase1 as a promising strategy for cancer immunotherapy in HCC." (PMID 38307859, 2024). "In this work, we identify higher expression of RNase1 in non-responders than in responders, and that the RNase1 level is associated with poor survival across several types of cancer." (PMID 38307859, 2024). "The different binding receptors of RNase1 on macrophage and CD4+ T cells might cause the differential responses in the two cell and cancer types." (PMID 38307859, 2024). "RNASE1 plays a significant role in the body’s innate immune response and contributes to the reduction of inflammation, ultimately leading to improved host defense and potential anti-cancer effects." (PMID 39044041, 2024). "Our findings indicate that non-responders have a high abundance of secreted RNase1, which is associated with a poor prognosis in various cancer types." (PMID 38307859, 2024). "Considering the antitumor role of RNase1 in the breast TME, we then determined whether the therapeutic efficacy of cancer immunotherapies, e.g., T cell-engaging bispecific antibody (T-bsAb) 57, can be improved with the aid of RNase1." (PMID 37416781, 2023). "Endothelial RNase1 was demonstrated as promising target for the development of novel treatment strategies in context of diverse pathologies, ranging from cardiovascular diseases over inflammatory and infectious pathologies to cancer." (PMID 33015070, 2020). "As we know, a number of cancer patients have a weakened immune system and are considered immunocompromised, which could mimic the conditions of our findings in nude mice demonstrating a tumor-promoting role of RNase1 through EphA4 ligand-receptor interaction." (PMID 37416781, 2023). "The secretory enzyme human ribonuclease 1 (RNase1) is involved in innate immunity and anti-inflammation, achieving host defense and anti-cancer effects; however, whether RNase1 contributes to adaptive immune response in the tumor microenvironment (TME) remains unclear." (PMID 37416781, 2023). "Silencing or knocking out RNase1 in FaDu and KPL4 cells resulted in a significant increase in T cell‐mediated cancer cell killing compared to that in the control cells." (PMID 39932384, 2025). "Results of immunohistochemical staining of tumor samples from HCC patients demonstrated a correlation between RNase1 expression and phospho-ALK expression in cancer cells and that ALK was expressed in most HCC cell lines." (PMID 38307859, 2024). "Subsequently, bovine pancreatic RNase A, bovine seminal RNase, Barnase, Ranpirnase (RNase I from Rana pipiens), human pancreatic RNase 1, human eosinophil-derived RNase (EDN) and angiogenin (Ang) all exhibit potent toxicity to cancer cells." (PMID 29510557, 2018). "The results indicated that even RNase1 lacking enzymatic activity still suppressed T cell‐mediated cancer cell killing." (PMID 39932384, 2025). "The results of these assays confirmed that the mutated RNase1 lost its ability to inhibit T‐cell cytotoxicity against cancer cells, supporting that disrupting the RNase1‐STAT1 interaction may prevent RNase1‐induced T‐cell dysfunction." (PMID 39932384, 2025). "Given that ALK blockade polarized RNase1-treated macrophages toward an M1-like phenotype and RNase1 upregulated PD-L1 in HCC cells, we asked whether combined treatment with an ALKi and αPD-1 can control cancer cells in vivo in the context of a complex TME." (PMID 38307859, 2024). "Large-scale preclinical studies and clinical trials are warranted to determine whether RNase1/ALK axis inhibition and combinational immune checkpoint blockade therapy are potentially effective therapeutic strategies for all major cancer types." (PMID 38307859, 2024).
cancer (continued). "Because researchers observed a positive correlation between MAPK pathway activity and PD-L1 expression in human cancer cells, we asked whether activation of EphA4/ERK signaling by RNase1 affects PD-L1 protein levels in HCCs." (PMID 38307859, 2024). "Heatmap analysis of the top differentially expressed genes (DEGs) delineated the signatures of each cell type among the six positive lymph nodes, with cancer cells highly expressing genes includingTFF1,AGR2,TFF3, and myeloid cells highly expressing genes includingC1QB,RNASE1 andAPOE." (PMID 36148946, 2022). "Similarly, despite the little evidence for a direct relationship between RNase1 release in endothelial cells and cancer progression, RNASE1 shows a good prediction performance based on raw data in TCGA." (PMID 36046240, 2022). "Notably, knockdown of mouse RNase1 resulted in reduced cancer growth only in immunocompetent but not in NOD SCID mice, suggesting that RNase1‐induced T‐cell dysfunction may contribute to cancer progression." (PMID 39932384, 2025).
tumor (60 papers, 2004 to 2025). "In addition, we observed a significant association between RNase1 expression and PD-L1 expression in tumor sections (P = 0.003)." (PMID 38307859, 2024). "Furthermore, the negatively correlation between CD8+ T-cell infiltration and RNase1 expression prompt us to ask whether RNase1 might associate with immunosuppressive tumor microenvironment in HCC." (PMID 38307859, 2024). "There was a strong positive correlation between tumor RNase1 level and paired plasma RNase1 concentration (R = 0.84), suggesting that plasma RNase1 have mainly originated from the patient’s tumor tissue." (PMID 40246819, 2025). "Compared with the plasma RNase1 level of 0.52 μg mL−1 in mice with RNase1‐overexpressing HCC tumor reported in a previous study,[11e] the serum RNase1 level (1.37 μg mL−1) of mice in the 4T1‐R1 group indeed showed an abnormally high concentration." (PMID 39932384, 2025). "Immunohistochemistry (IHC) staining also indicated higher levels of RNase1 level in the tumor tissues than normal lung tissues." (PMID 40246819, 2025). "Macrophages_LYVE1 also expressed high levels of LYVE1, RNASE1, STAB1, CD163, and MARCO, which are associated with macrophage function and tumour immunosuppression." (PMID 40759637, 2025). "Tumor-secreted RNase1 also induces TAM polarization toward a tumor-promoting phenotype via the ALK signaling pathway, suppressing CD8+ T cell activity." (PMID 40764998, 2025). "Meanwhile, we observed significantly decreased percentages of dendritic cells (DCs; CD11chi), effector lymphocytes, and B cells when RNase1 was highly secreted by tumor cells." (PMID 38307859, 2024). "RNase1 induces the polarization of macrophages towards a tumor growth-promoting phenotype through activation of the anaplastic lymphoma kinase (ALK) signaling pathway." (PMID 38307859, 2024). "DAPL1 (larger diameter) was expressed in the tumor region, and RNASE1 (larger diameter) was expressed in the stromal region." (PMID 39135097, 2024). "Our study provides an understanding of the cross-talk between tumor and immune cells in the TME, and identifies RNase1 as a potential plasma biomarker to overcome tumor-associated macrophage (TAM)-mediated immunosuppression in HCC patients." (PMID 38307859, 2024). "Here the authors report that RNase1 levels predict response to nivolumab (anti-PD1) in patients with HCC and that RNase 1 overexpression correlates with an immunosuppressive tumor microenvironment in HCC preclinical models." (PMID 38307859, 2024). "We found that RNase1 was expressed in the tumor-cell-conditioned medium derived from six out of nine HCC cell lines (Hepa1-6, HepG2, HA22T, HA59T, Tong, and Mahlavu)." (PMID 38307859, 2024). "Immunosuppressive cluster C5, which highly expresses C1QA, APOE and RNASE1, was at the terminal state of differentiation and played an important role in the formation of an immunosuppressive tumor microenvironment." (PMID 38408082, 2024). "To evaluate the impact of tumor-cell-secreted RNase1 on the TME, we measured the levels of RNase1 in HCC cell lines." (PMID 38307859, 2024). "Significantly, in the presence of the immune system, the 4T1 tumor-bearing mice with RNase1 ectopic expression exhibited less tumor volume than did the control mice (red vs. black)." (PMID 37416781, 2023). "In summary, our findings provide insights into the functional role of RNase1 in the adaptive immune system by enhancing T cell activation to eliminate tumor growth." (PMID 37416781, 2023). "We graphed the tumor volume as a continuous variable in a waterfall plot, which showed that RNase1-expressing 4T1 tumor-bearing mice had a higher response rate compared to the control mice." (PMID 37416781, 2023). "Together, these results strongly support the raised possibility that RNase1-mediated tumor suppression is T cell dependent." (PMID 37416781, 2023).
tumor (continued). "Several types of RNases such as Barnase, Binase, Ranpirnase, human pancreatic RNase 1 (HP-RNase 1), bovine pancreatic RNase A, bovine seminal RNase, human eosinophil-derived RNase and angiogenin have exhibited potent toxicity on tumor cells." (PMID 34488747, 2021). "Application of RNase1 has also been discussed as an antitumoral agent; RNase1 administration reduced tumor volume and weight, and increased the area of necrosis in vivo in xenograft mice models." (PMID 31680858, 2019). "In a number of studies, an increase in the cytotoxicity of RNase A and RNase 1 was achieved by conjugating these RNases with peptides, proteins and antibodies, which increased the efficiency of their capture by tumour cells." (PMID 31572192, 2019). "Indeed, our data demonstrated that treatment with an ALKi alone decreased CD206+ TAM infiltration and reduced tumor weights in the RNase1-expressing orthotopic HCC model." (PMID 38307859, 2024). "Furthermore, mice implanted with HCC cells that overexpress RNase1 exhibit immunosuppressive tumor microenvironments and diminished response to anti-PD-1 therapy." (PMID 38307859, 2024). "Considering that both the BALB/c and the J:NU mouse models used in this study harbor NK cell lineages, we next aimed to determine whether T cells act as major mediators in RNase1-regulated tumor suppression." (PMID 37416781, 2023). "Collectively, these results showed that RNase1 contributed to a significant induction of CD4+ Th1, CD4+ Th17, and NK cells, which associate with antitumor immunity, as well as a reduction of immunosuppressive MDSCs that associate with pro-tumor activity." (PMID 37416781, 2023). "It would be worthwhile to elucidate whether the binding of RNase1 to EphA4 on CD4+ T cells stimulates their migration to tumor tissue for maintaining immune homeostasis." (PMID 37416781, 2023). "Among them, Module2 (highly express RNASE1, C1QA, CD163, CD14, C1QC, FCGRT, and MS4A7) and Module10 (highly express APOC1, CTSB, CTSL, and TYROBP) are more likely to display the characteristics of tumor-associated macrophages (TAMs)." (PMID 35990663, 2022). "Moreover, there was a strong positive correlation between mice serum RNase1 concentration and tumor size (R = 0.89), raising an interesting notion that RNase1 concentration and phospho-ALK may serve as biomarkers to identify the RDAA positive tumors." (PMID 40246819, 2025). "The results showed that R1‐5A expressed in MDA‐MB‐231 abolished the RNase1‐promoted increases in tumor volume and weight, suggesting that the RNase1‐STAT1 interaction in CD8+ T cells may be crucial for RNase1 to inhibit CD8+ T‐cell cytotoxicity against cancer cells in vivo." (PMID 39932384, 2025). "To minimize the issues that might be caused by the compound 1-EphA2 association, hereinafter we focused on RNase1 to further pursue how RNase1 contributes to antitumor immunity and whether EphA4 is involved in RNase1-mediated tumor suppression in the breast TME." (PMID 37416781, 2023). "Targeting the RNase1/ALK axis reprograms TAMs, enhances T cell recruitment, and restores anti-tumor immunity." (PMID 40764998, 2025). "In the previous study, the immune cell profile was analyzed through cytometry by time of flight analysis in HCC mouse tumor tissues and an increased M2‐like TAM in high RNase1‐expressing tumors was observed." (PMID 39932384, 2025). "On the other hand, immune system-related genes, including SLC16A10, RNASE1, and RNASE6, function in immune responses, antimicrobial activity, and enhancing anti-tumor immunity." (PMID 38461288, 2024). "Interestingly, we observed increased viability and invasion in Hep3B and Huh7 cells upon RNase1 treatment, which could be repressed by pretreatment with crizotinib or Alectinib, suggesting that ALK is also essential for the biological activities of RNase1 in HCC tumor cells." (PMID 38307859, 2024).
tumor (continued). "Exploration of the expression network indicated that inflammatory genes (CXCL8, CXCL3, PIGR, and RNASE1) and Wnt pathway genes (GAST, REG1A, TFF3, and ZG16B) are upregulated in tumor stem cells of UGICs." (PMID 35646860, 2022). "Also, there was a good correlation between RNase1 and ALK phosphorylation through the tumor tissue IHC." (PMID 40246819, 2025). "RNase1 promotes tumor growth in immunocompetent, but not in immunodeficient, mouse models and inhibits CD8+ T‐cell activity in vivo." (PMID 39932384, 2025). "Given that RNase1 increases cell frequencies of CD4+ Th1, Th17, and NK cells, it is possible that RNase1 increases CD4+ T cell-specific subsets, which in turn activate NK cell function to generate a more robust immune response for eradicating tumor cells." (PMID 37416781, 2023). "Interestingly, subcutaneous tumor generation was observed in nude mice (7/8) injected with RDAA NIH3T3 cells but not those expressing ALK (0/8) or RNase1 (0/8) alone and NIH3T3 control (0/8)." (PMID 40246819, 2025). "However, the current study revealed that knockdown of RNase1 in 4T1 cells decreased tumor growth and did not affect CD4+ T‐cell activity in vivo." (PMID 39932384, 2025). "Therefore, RNase1 should promote a state of T‐cell exhaustion and impair T‐cell activation and effector function to inhibit CD8+ T‐cell cytotoxicity, thereby promoting tumor growth, which we observed in this study." (PMID 39932384, 2025). "The discrepancy may mainly come from tumor or cell-type specificity because HT-29 cells, unlike 4T1 cells, express low or undetectable levels of EphA4 64, thus stopping RNase1 from binding to and activating EphA4 signaling in HT-29 cells." (PMID 37416781, 2023). "Indeed, De Lorenzo and D'Alessio clarified that the immune-RNase 1 fusion proteins were not only non-toxic outside the tumor cells but also non-immunogenic." (PMID 31849926, 2019).
infection (22 papers, 2012 to 2024). The state of being infected such as from the introduction of a foreign agent such as serum, vaccine, antigenic substance or organism. "In order to confirm the eRNA-mediated effect on pneumococcal adherence and invasion, eRNA-preincubated lung epithelial cells were treated with 1 ng or 10 ng RNase1 prior to the infection with SpΔply pneumococci." (PMID 27892961, 2016).
infectious disease (4 papers, 2020 to 2023). A disorder directly resulting from the presence and activity of a microbial, viral, or parasitic agent in humans. "This sensitization reaction might favor the development of specific endogenous antagonists such as RNase1 to prevent hyperinflammatory reactions during processes of sterile inflammation or infectious diseases." (PMID 35563745, 2022).
RNASE1 also shares sentences with these, for which no sentence is quoted: Lewis lung carcinoma (6 papers); ovarian carcinoma (6); hepatocellular carcinoma (5); cardiovascular diseases (4); bacterial infections (3); colorectal cancer (3); liver cancer (3); bladder cancer (2); colon adenocarcinoma (2); dengue (2); esophageal cancer (2); glioblastoma (2); lung squamous cell carcinoma (2); lupus (2); Myeloma (2); neurodegenerative disease (2); ovarian endometriosis (2); thrombosis (2); acute myeloid leukemia (1); amyloidosis (1); amyotrophic lateral sclerosis (1); aneurysm (1); anorexia nervosa (1); cervical cancer (1); Cognitive impairment (1); colorectal tumour (1); endothelial dysfunction (1); esophageal squamous cell carcinoma (1); Ewing sarcoma (1); graft versus host disease (1).
A further 33 diseases each share a sentence with RNASE1 in 1 paper.